IL5 (interleukin 5)
Diseases named in the same sentence as IL5 in open-access papers (continued):
Sharing a sentence is not in itself a finding about the gene and the disease.
glaucoma (5 papers, 2012 to 2021). Increased pressure in the eyeball due to obstruction of the outflow of aqueous humor. "While the majority of changes we observed were in pro-inflammatory mediators, our results suggest that anti-inflammatory cytokines may play a compensatory role early in glaucoma prior to transport loss, as evidenced by early elevations in retinal IL-5 and IL-10." (PMID 26376776, 2015). "IL-4, IL-5, CCL3, and G-CSF was detected in less than 50% of samples in both control and glaucoma groups and therefore were not included in further analysis." (PMID 22355254, 2012).
glioma (5 papers, 2011 to 2023). A benign or malignant brain and spinal cord tumor that arises from glial cells (astrocytes, oligodendrocytes, ependymal cells). "Stimulation with a variety of peptide antigens over-expressed by gliomas is associated with a profound reduction in the IFN-γ/IL-5 ratio in GBM patients relative to healthy subjects." (PMID 23186108, 2012). "Significant differences in the concentrations of IFN-γ, TNF-α, and IL-5 were observed only when NY-ESO-1 specific T cells were co-cultured with decitabine-treated T98 glioma cells (p < 0.0001)." (PMID 22060015, 2011). "The result suggested that KCNIP, IGFBP2, IL5, and SAMD9L were independent poor prognostic factors for GBM and glioma." (PMID 36762114, 2023). "Moreover, we found that PDCD4 regulates the expression of IL-5, CCL-5, VEGF, and CXCL10 in glioma cells, which provides a therapeutic opportunity to block these cytokines." (PMID 33304903, 2020). "Thus, treatment of T98 glioma cells with decitabine results in significantly enhanced NY-ESO-1 specific T cell recognition and secretion of Th1-type cytokines along with IL-5." (PMID 22060015, 2011).
Headache (5 papers, 2018 to 2026). Cephalgia, or pain sensed in various parts of the head, not confined to the area of distribution of any nerve. "Analysis of the association between increased cytokine levels and ZIKV symptoms indicated that CXCL10 (p = 0.0029) was associated with exanthema, while IL-5 (p = 0.0496) was linked to headache." (PMID 37235332, 2023). "Remarkably, headache in our study was associated with significantly high levels of IL-5 (p = 0.0496), corresponding to the findings of previous studies." (PMID 37235332, 2023). "Moreover, headache was found to be associated with IL-5 (p = 0.0496)." (PMID 37235332, 2023). "Of note, we found that higher levels of IP-10 and IL-5 in ZIKV-infected individuals were strongly associated with exanthema and headache, respectively." (PMID 29774022, 2018). "We found significantly higher levels of IL-1ra in ZIKV-infected individuals with arthralgia and IL-5 in those with headache." (PMID 29774022, 2018). "Headache was predicted mainly by IL-5 and to a lesser extent by MIP-1β, while arthralgia was predicted by IL-1ra and IL-7." (PMID 29774022, 2018). "Further longitudinal study is required to determine if the small change in plasma IL-5 level correlates with headache frequency, initiation of CGRP mAb, or whether this result represents a type I error." (PMID 40991059, 2025). "Zika virus-infected subjects who reported headaches showed higher plasma levels of TNF-α, IL-17A, IL-2, IL-9, IL-12p70, MIP-1α, G-CSF, GM-CSF, and VEGF, and significantly higher levels of IL-5 (p = 0.0015) compared to those without headache." (PMID 29774022, 2018).
heart failure (5 papers, 2021 to 2025). Inability of the heart to pump blood at an adequate rate to meet tissue metabolic requirements. "In the case-control analysis, we observed that anti-IL5 use significantly reduced heart failure by reducing SABD overuse (eTable 11)." (PMID 40823190, 2025). "The concentrations of IL-5, IL-6 and IL-9 were significantly higher in the saliva of heart failure patients with both NS and HS compared to the control group, while IL-4 level was significantly higher only in heart failure patients with HS." (PMID 36300113, 2022).
Hypertension (5 papers, 2021 to 2026). The presence of chronic increased pressure in the systemic arterial system. "Interleukin‐5 (IL‐5), IL‐6 and IL‐12 levels correlated with mean CT in acute CSC (p = 0.008, p = 0.003 and p = 0.044, respectively), while IL‐8, IL‐6 and TNF‐α plasma levels correlated with hypertension in chronic CSC (p = 0.005, p = 0.033 and p = 0.001, respectively)." (PMID 32701204, 2021).
mastocytosis (5 papers, 2011 to 2025). A clonal myeloproliferative neoplasm characterized by the proliferation and accumulation of neoplastic mast cells in one or multiple organs or organ systems. "Allergy and helminths induce strongly Th2-skewed responses associated with cytokines such as IL-4, IL-5, and IL-13, with mastocytosis, eosinophilia, and antibody class-switching to produce IgE." (PMID 27980457, 2016). "In human fascioliasis, in the acute phase, a predominant Th2 response takes over, with production of IL-4, IL-5, as well as mastocytosis, hypereosinophilia and IgE production and the absence of IFN-gamma and IL-2." (PMID 40864127, 2025).
myocarditis (5 papers, 2021 to 2026). Myocarditis is a condition that is characterized by inflammation of the heart muscle (myocardium). "In one case report, patients with vaccine-induced myocarditis had increased levels of interleukin 1 (IL-1) receptor antagonist, interleukin 5 (IL-5), and interleukin 16 (IL-16)." (PMID 36006288, 2022). "The patients with myocarditis also showed high levels of IL-1 receptor antagonist (interleukin 1), IL-5, and IL-16 but no proinflammatory cytokines, for example, IL-6, tumor necrosis factor, IL-1B, IL-2 or interferon-γ." (PMID 36498573, 2022).
pollen allergy (5 papers, 2014 to 2026). "It would be interesting to investigate whether this sub-group of IL-5 responders might represent a risk group in whom HDM immunotherapy would be an effective preventive intervention, as shown in the PAT study for pollen allergy." (PMID 24875149, 2014). "Finally, in an RCT including adults with pollen allergy, CLA supplementation significantly reduced sneezing during pollen season, and production of TNF-alfa, IFN-gamma, and IL-5." (PMID 33339279, 2020).
sarcoidosis (5 papers, 2012 to 2025). Sarcoidosis is a multisystemic disorder of unknown cause characterized by the formation of immune granulomas in involved organs. "Sarcoidosis patients had decreased levels of IL-1β, IL-5, IL-8, IL-12p70, TNF-α, angiogenin, C3a, C4a, RANTES, and MCP-1 and increased levels of IL-2, IL-4, IL-6, IL-13, IFN-γ, and VEGF." (PMID 40725075, 2025). "Our in silico analyses also revealed that IL-3 and IL-5 pathways, which signal via the shared βc receptor, are concurrently activated in progressive lung sarcoidosis, with the combined (IL-3, IL-5, and GM-CSF) pathway exhibiting the highest enrichment in both GSEA and GSVA results." (PMID 41476976, 2025). "However, despite similar local responses at the site of disease, the systemic response varies between individuals as evidenced by significantly higher serum IL-4 levels (and the possible elevation of IL-5 and IL-13) in sarcoidosis." (PMID 22815689, 2012). "However, the concentration of IL-5 in EGPA patients was higher than in other ILDs or OLDs, with a significant difference in comparison to sarcoidosis (p = 0.0002)." (PMID 40725075, 2025). "Whilst not raised in fibrotic sarcoidosis (compared to healthy controls), IL-5 was significantly decreased in nonfibrotic compared to fibrotic sarcoidosis, suggesting that reduced IL-5 is protective against fibrosis." (PMID 36543347, 2022).
Sjögren’s syndrome (5 papers, 2015 to 2022). "The study aimed to quantify certain cytokines involved in the pathomechanism of primary Sjögren syndrome (IL2, IL5, IL6, IL10, IL13, TNFα, IFNγ) and determine their common clinical correlation." (PMID 36143051, 2022). "On other hand, Th2-associated cytokines are only important in the case of dry eye disease (IL4, IL5, IL33) and Sjögren’s syndrome (IL33)." (PMID 31810226, 2019).
Abdominal obesity (4 papers, 2015 to 2022). Excessive fat around the stomach and abdomen. "General obesity was associated with significantly elevated levels of IL-5, IL-10, IL-12, IL-13, IFN-γ and TNF-α, central obesity with significantly elevated IL-5, IL-10, IL-12, IL-13 and IFN-γ-levels." (PMID 25781614, 2015). "After Bonferroni-correction, IL-5, IL-12 and IL-13 were found to be elevated in both general and central obesity, and IL-10 elevated in the central obese." (PMID 25781614, 2015). "In obese adolescent girls, TNF-α, IL-4 and IL-5 levels were higher in those with central obesity." (PMID 25781614, 2015). "Among the tested cytokines, IL-5, IL-10, IL-12, IL-13 and IFN-γ were elevated in both general and central obesity." (PMID 25781614, 2015). "Looking specifically at central obesity, higher levels of IL-5, IL-6, IL-12, IL-13, and IFN-γ were reported in participants with abdominal obesity compared to those without." (PMID 36364892, 2022). "Looking specifically at central obesity, we found higher levels of IL-5, IL-10, IL-12 and IL-13 and IFN-γ in participants with compared to those without central obesity." (PMID 25781614, 2015). "In the post-hoc ANOVA, subjects with central obesity showed significantly elevated serum concentrations of IL-5, IL-10, IL-12, IL-13 and IFN-γ compared to the group without central obesity (after Bonferroni correction, differences remained significant for all but IFN-γ)." (PMID 25781614, 2015).
AIDS (4 papers, 2018 to 2022). A syndrome resulting from the acquired deficiency of cellular immunity caused by the human immunodeficiency virus (HIV). "It has been reported that acquired immune deficiency syndrome patients with decreased levels of DHEA-S show excessive cytokine production by Th2 cells (IL-4, IL-5, IL-6, and IL-10) and suppression of other cytokines (IL-2, IFN-γ, IL-12)." (PMID 29694639, 2018). "On the other hand, the Th2-specific cytokines, i.e., IL-4, IL-5, IL-6, IL-10, and IL-13, are associated with disease progression and lead to the progression of HIV infection to AIDS." (PMID 31641392, 2019). "However, low levels of IL-5 have been associated with disease progression in HIV infection, and while GM-CSF has been suggested as a possible treatment for neutropenia in AIDS patients, increased infiltration of inflammatory mediators in some patients is alarming." (PMID 35805128, 2022).
breast tumor (4 papers, 2016 to 2024). "This novel effector mechanism is mediated by tumor-infiltrating Th2 cells releasing IL-3, IL-5, and GM-CSF, which bind to a shared receptor on breast tumor cells." (PMID 35657353, 2022). "Th2 cells directly blocked breast carcinogenesis by secreting IL-3, IL-5, and GM-CSF, which signaled to their common receptor expressed on breast tumor cells." (PMID 35657353, 2022). "Breast tumors infiltrated by MMP-11+ mononuclear inflammatory cells are more likely to metastasize, have high levels of interleukin (IL)-1, IL-5, IL-6, IL-17, interferon (IFN), and NFB, and an increased CD68+/(CD3+CD20+) cell ratio at the invasive front." (PMID 39190284, 2024). "Furthermore, STAT3 and IL5 but not GM-CSF were differentially expressed between breast tumor tissue and normal tissue (p value = 2.5 × 10−3, 4.5 × 10−4 and 0.63, respectively)." (PMID 26621531, 2016).
bullous pemphigoid (4 papers, 2018 to 2025). Bullous pemphigoid (BP) is the most common form of autoimmune bullous dermatosis. "- Bullous pemphigoid displays a clear Th2-mediated inflammatory response, characterized by IL-4, IL-5, and IL-13, eosinophil recruitment and pruritus." (PMID 41479908, 2025). "In a recent published study, it was shown that IL-5-activated eosinophils directly contribute to blister formation in the presence of bullous pemphigoid autoantibodies, in an ex vivo human disease model." (PMID 30524436, 2018). "The primary goal of this research is to assess the relationship between serum levels of IL-31, IL-5, and SII and disease status among patients with bullous pemphigoid (BP)." (PMID 41169429, 2025).
celiac disease (4 papers, 2014 to 2024). An autoimmune genetic disorder with an unknown pattern of inheritance that primarily affects the digestive tract. "Moreover, the Th2-associated cytokines IL-5, IL-10 and IL-13 were elevated in children with coeliac disease compared to controls." (PMID 25212572, 2015). "In patients with active celiac disease, eosinophils from the gut mucosa were shown to be positive for IL-5 mRNA, and following treatment with a gluten-free diet, the numbers of IL-5+ eosinophils declined." (PMID 25426119, 2014). "Serum samples were collected in 19 of 26 children with coeliac disease after starting a gluten-free diet after 1·5 ± 0·36 years [median ± standard deviation (s.d.)] and analyses performed for cytokines IFN-γ, IL-5, IL-10, IL-12p70 and IL-13." (PMID 25212572, 2015). "Our finding of cytokines IL-5, IL-10 and IL-13 belonging to the Th2 response being elevated significantly in coeliac disease was surprising, as a Th2 cytokine pattern has not been considered previously to be central in the immune reaction in coeliac disease." (PMID 25212572, 2015). "IL-5, involved in eosinophilic differentiation, has not been studied previously in serum of coeliac disease patients, but has been detected in eosinophilic cells from intestinal mucosa of coeliac disease patients." (PMID 25212572, 2015).
cerebral malaria (4 papers, 2015 to 2023). A sequestration of Plasmodium falciparum in the brain, which can cause coma and/or seizures. "IL-5 is a potent activator of eosinophils and together with elevated IgE levels is typically associated with cerebral malaria." (PMID 25889652, 2015).
Chronic colitis (4 papers, 2015 to 2022). A chronic inflammatory disease of the large intestine (colon, cecum and rectum). "In our study, the lack of effects of SB3 treatment on the number of EPoCs in the bone marrow of mice with chronic colitis coincided with elevated IL-5 levels in their serum after treatment." (PMID 35887133, 2022). "This suggests that in an acute damage model, mobilization of mature eosinophils from the BM to intestine is sufficient, whereas sustained chronic colitis requires IL-5-dependent eosinopoiesis." (PMID 26200014, 2015). "Moreover, IL-5 blockade hindered eosinophil activities and ameliorated intestinal inflammation in a model of chronic colitis induced by T cell transfer into Rag−/− mice." (PMID 35887133, 2022). "Together the data suggest that IL-5 plays a homeostatic role maintaining basal levels of eosinophils in the intestine, whereas GM-CSF promotes their activation and deleterious effector functions in chronic colitis." (PMID 26200014, 2015). "Accordingly, colonic GM-CSF, but not IL-5, mRNA and protein levels were augmented in chronic colitis, possibly highlighting a more homeostatic role for IL-5 compared with the more activation-induced functions of GM-CSF." (PMID 26200014, 2015). "The level of IL-4 and IL-5 with anti-CD3 and anti-CD28 mAb stimulation and without any stimulation was markedly increased in the IL-33-treated chronic colitis group compared with the control group." (PMID 30539029, 2018).
chronic cystitis (4 papers, 2010 to 2021). Recurrent infections of the urinary bladder. "We have found a strong association between elevated serum IL-5 at 24 hpi and the development of chronic cystitis." (PMID 20811584, 2010). "Redevelopment of chronic cystitis was significantly associated with the onset of severe pyuria and elevated serum IL-5, G-CSF, and KC at 24 hpi, compared to mice that resolved the challenge infection, whether or not they had a history of chronic cystitis (data not shown)." (PMID 20811584, 2010). "C3H/HeN mice that progress to chronic cystitis upon single inoculation can be predicted by elevated serum levels of IL-5, IL-6, KC, and G-CSF at 24 hpi." (PMID 25569799, 2015). "We identified elevated IL-5, IL-6, G-CSF, and KC as a serum biomarker signature prognostic of the development of chronic cystitis in C3H mice." (PMID 20811584, 2010). "As well, there were trends toward higher serum IL-5 and IL-6 levels in mice that would develop chronic CFT073 cystitis, but, unlike with UTI89-infected mice, the differences were not statistically significant." (PMID 30543708, 2018).
colon cancer (4 papers, 2019 to 2021). "Our findings identify ILC2s as the main IL-5 producer in the colon tumour microenvironment, suggesting that ILC2s may be a key player in mediating tumour protection through the activation of eosinophils, although this remains to be established." (PMID 33535624, 2021).
dry eye (4 papers, 2015 to 2022). "TUDCA supplementation also led to the transcriptional repression of CXCL8 and IL5, two inflammatory mediators associated with dry-eye pathogenesis." (PMID 35562919, 2022). "We show that the alleviation of ER stress with the chemical chaperone TUDCA prevents cell death by reducing nuclear DNA fragmentation and caspase-3 activation, and represses the transcription of two inflammatory mediators, CXCL8 and IL5, that are associated with dry-eye pathogenesis." (PMID 35562919, 2022). "Interestingly, our results also indicate that TUDCA reduces the expression of IL5, a major maturation and differentiation factor for eosinophils, although the significance of this finding for the pathophysiology of dry eye remains unclear." (PMID 35562919, 2022). "Increases of IFN-γ, IL-2, IL-4, IL-5, IL-13 or IL-β1 in SAC; TSLP in both PAC and SAC; and IL-17, IL-21 and IL-22 in dry eyes have been observed in different studies." (PMID 35935953, 2022).
exanthema (4 papers, 2018 to 2025). "The elevation of Th2-Associated Cytokines (IL-5, IL-24) typically associated with allergic and atopic conditions could explain the allergic manifestations like skin rash and pruritus observed in the patient." (PMID 40557145, 2025). "Interestingly, exanthema was strongly associated with IFN-γ (p = 0.0017), IL-4 (p = 0.0018), IL-5 (p = 0.0047), and CXCL10 (p = 0.0029)." (PMID 37235332, 2023). "Based on the significantly higher incidence of skin rashes occurring with MIS-C and the higher levels of cytokines (IL-5, IL-8, IL-13, and IL-33) known to influence eosinophil activity, we performed a further evaluation of eosinophils and ELR." (PMID 38932242, 2024). "Despite increased levels of IL-5 in ZIKV-infected individuals, we observed normal levels of eosinophils and IgE, suggesting that exanthema, the most frequent symptom of our cohort (80.5%), may not involve eosinophils and IgE." (PMID 29774022, 2018).
glioblastoma (4 papers, 2015 to 2025). The most malignant astrocytic tumor (WHO grade IV). "IRE1α-XBP1 stimulates interleukin-5 (IL-5) and interleukin-13 (IL-13), mediating a proliferative drive; however, these pro-inflammatory cytokines can also be counterproductive, promoting lung metastasis and glioblastoma invasion." (PMID 41301006, 2025).